CDK7 (cyclin dependent kinase 7)
Diseases named in the same sentence as CDK7 in open-access papers (continued):
Sharing a sentence is not in itself a finding about the gene and the disease.
cardiac hypertrophy (1 paper, 2025). "However, simultaneous inhibition of CDK7, CDK12, and CDK13 has been found necessary for potent and consistent antihypertrophic responses, suggesting that CDK7 could also play a pivotal role in cardiac hypertrophy development." (PMID 39800748, 2025).
Cirrhosis (1 paper, 2017). A chronic disorder of the liver in which liver tissue becomes scarred and is partially replaced by regenerative nodules and fibrotic tissue resulting in loss of liver function. "Compared with patients without cirrhosis, the expression of CDK7 was downregulated in patients with cirrhosis, whereas the expression of SFN was upregulated in patients with cirrhosis." (PMID 28266596, 2017).
colitis (1 paper, 2024). Inflammation of the colon. "In order to explore the effect of THZ2, a small molecule inhibitor of CDK7 on colitis, we generated acute colitis with DSS in BALB/c mice." (PMID 38540292, 2024).
diabetic nephropathy (1 paper, 2018). "CDK7, a putative thiol-related gene, is regulated by glucose in renal cells and exerts oxidative stress, which may become a potential target for the treatment of diabetic nephropathy." (PMID 30521536, 2018).
ductal breast carcinoma (1 paper, 2021). "CDK7 mRNA was also elevated in lobular breast carcinoma (fold change = 1.761) and in ductal breast carcinoma (fold change = 1.991) in Zhao’s dataset." (PMID 33686962, 2021).
endometrial carcinoma (1 paper, 2015). A malignant tumor arising from the epithelium that lines the cavity of the uterine body. "Thus, high CDK7 expression may be one of the mechanisms underlying the resistance of endometrial carcinoma cells to platinum-based chemotherapy." (PMID 25411854, 2015). "Additional research following these studies revealed that the expression levels of CDK7 were lowest in normal endometrium, increased during endometrial hyperplasia and peaked in endometrial carcinoma tissues." (PMID 25411854, 2015). "Further in-depth studies using CDK7 as a target for endometrial carcinoma treatment should be performed." (PMID 25411854, 2015). "The aim of the present study was to determine the effect of cyclin-dependent kinase 7 (CDK7) silencing on the sensitivity of the HEC-1-A endometrial carcinoma cell line to cisplatin [cis-dichlorodiammineplatinum (II), or DDP]." (PMID 25411854, 2015). "Based on preliminary research, the present study used siRNA technology to silence CDK7 expression in the HEC-1-A endometrial carcinoma cell line." (PMID 25411854, 2015). "Downregulation of CDK7 expression levels in HEC-1-A endometrial carcinoma cells via the transfection of CDK7 siRNA may significantly enhance cancer cell sensitivity to cisplatin chemotherapy and increasing apoptosis." (PMID 25411854, 2015). "CDK7 is a novel promising treatment for endometrial carcinoma that requires further in-depth study." (PMID 25411854, 2015). "The CDK7-423 siRNA fragment exhibited the most marked silencing of CDK-7 (>70%), and was chosen for the subsequent experiments in HEC-1-A endometrial carcinoma cells." (PMID 25411854, 2015).
endometriosis (1 paper, 2024). The growth of functional endometrial tissue in anatomic sites outside the uterine body. "The PPI network analysis reveals hub genes, including BCL2, CCNA2, CDK7, EGF, GAS6, MAP3K7, and TAB2, which emerge as pivotal players in endometriosis progression." (PMID 39108650, 2024).
Ewing sarcoma (1 paper, 2019). A small round cell tumor that lacks morphologic, immunohistochemical, and electron microscopic evidence of neuroectodermal differentiation. "Analyses of four cell lines and three primary tumors established the super-enhancer landscape of Ewing sarcoma, and revealed that super-enhancer-associated genes were exceptionally sensitive to inhibition of CDK7." (PMID 30496486, 2019). "In the current study, we observed that Ewing sarcoma cells were sensitive to transcriptional perturbation, mediated by CDK7 suppression." (PMID 30496486, 2019). "Depletion of CDK7 expression by shRNAs confirmed that CDK7 was indispensable for the viability of Ewing sarcoma cells." (PMID 30496486, 2019). "Given that transcriptional dysregulation typifies the biology of Ewing sarcoma, we first evaluated the anti-tumor effect of transcription inhibition in Ewing sarcoma cells by testing THZ1, which is a newly developed covalent inhibitor of cyclin-dependent kinase 7 (CDK7)." (PMID 30496486, 2019).
fibrosis (1 paper, 2025). the formation of excess fibrous connective tissue in an organ or tissue in a reparative or reactive process. "Pediatric DOX injection induced late cardiotoxicity including systolic and diastolic dysfunction, cardiac fibrosis and cardiomyocyte atrophy, which were alleviated by treatment with the CDK7/12/13 inhibitor THZ1." (PMID 41101390, 2025).
follicular lymphoma (1 paper, 2024). Follicular lymphoma is a form of non-Hodgkin lymphoma characterized by a proliferation of B cells whose nodular structure of follicular architecture is preserved. "Treatment with CDK7/9 inhibitors together with venetoclax resulted in increased DLBCL, follicular lymphoma, and marginal zone lymphoma patient sample cell death." (PMID 38893249, 2024).
heart failure (1 paper, 2022). Inability of the heart to pump blood at an adequate rate to meet tissue metabolic requirements. "Furthermore, it is expected that gene deletion in any one cellular compartment would only give a partial protection from heart failure pathogenesis and that simultaneous CDK7/12/13 inhibition in multiple cell types, as occurs with THZ1, is required for full therapeutic effects." (PMID 35896549, 2022).
hepatoblastoma (1 paper, 2023). Hepatoblastoma (HB) is a malignant hepatic tumor and is the most common pediatric liver cancer. "After deriving cell lines from the mouse model, we map cancer dependency genes using CRISPR-Cas9 screening and identify druggable targets shared with human hepatoblastoma (e.g., CDK7, CDK9, PRMT1, PRMT5)." (PMID 37414763, 2023). "Although the functions of CDK7 in hepatoblastoma have yet to be explored, CDK7 inhibition disrupts the transcriptional dependency of MYC-driven cancer." (PMID 37414763, 2023).
hypokalaemia (1 paper, 2018). "Moreover, it is necessary to pay attention to the side effect profile of the combination of other CDK7 inhibitor and DMARD, which may include tolerable and limited gastrointestinal disturbance, skin rash, reversible transaminitis and hypokalaemia." (PMID 29083085, 2018).
Infertility (1 paper, 2014). "In our suppressor screen, CDK-7 was identified as a moderate suppressor of the WEE-1.3 depletion infertility phenotype." (PMID 25298536, 2014).
intervertebral disc degeneration (1 paper, 2023). "However, the underlying mechanism of transcriptional abnormalities in intervertebral disc degeneration and whether CDK7 inhibitors can delay intervertebral disc degeneration remain unexplored." (PMID 37012048, 2023).
keloid (1 paper, 2025). An irregularly shaped, elevated mark on the skin caused by deposits of excessive amounts of collagen during wound healing. "In summary, we identified two novel keloid-associated genes, CDK7 and DDB2, through bioinformatics analysis." (PMID 41347148, 2025). "Our findings demonstrate that CDK7 and DDB2 are promising biomarkers for diagnostic and potential therapeutic targets in keloid, providing novel insights into its pathogenesis and offering promising druggable targets." (PMID 41347148, 2025). "Integrated bioinformatics and basic experimental approaches were used in this study to detect and confirm two biomarkers, CDK7 and DDB2, associated with keloid." (PMID 41347148, 2025). "Through WGCNA and PPI network analyses, we identified two key genes, CDK7 and DDB2, associated with keloid." (PMID 41347148, 2025). "ROC analytical frameworks were established to evaluate the diagnostic potential of CDK7 and DDB2 as keloid biomarker candidates." (PMID 41347148, 2025). "Given the pathological classification of keloid as benign fibroproliferative neoplasms, CDK7 might also function as a possible treatment target for keloid therapy." (PMID 41347148, 2025). "These experiments verified that CDK7 and DDB2 expression in keloid tissue cells was markedly elevated compared to normal tissues, further supporting the reliability and research value of our analysis." (PMID 41347148, 2025). "Second, the specific roles of CDK7 and DDB2 in keloid pathogenesis are not fully understood and require molecular biology experiments and rigorously designed multicenter studies for validation." (PMID 41347148, 2025). "Basic experiments confirmed higher expression of CDK7 and DDB2 in keloid tissue compared to normal skin." (PMID 41347148, 2025). "Based on degree scores, CDK7 and DDB2 were identified as key genes, with their expression levels in keloid and control groups visualized via box plots." (PMID 41347148, 2025). "Further validation via qRT-PCR, western blotting, and immunofluorescence confirmed significantly elevated expression of CDK7 and DDB2 in keloid specimens relative to normal specimens." (PMID 41347148, 2025). "Although the specific molecular mechanism still needs further research, this provides a new perspective for understanding the role of CDK7 and DDB2 in the pathogenesis of keloid." (PMID 41347148, 2025). "Finally, we validated our bioinformatics findings by assessing CDK7 and DDB2 expression levels in tissues from six keloid patients and six normal subjects using qRT-PCR, western blotting, and immunofluorescence." (PMID 41347148, 2025). "Lastly, although CDK7 and DDB2 are recognized in oncology research, keloids are not classified as true tumors, necessitating further experimentation to substantiate our findings." (PMID 41347148, 2025). "Currently, research has not clearly found whether CDK7 and DDB2 can affect the pathogenesis of keloid through the TGF-β/Smad signaling pathway." (PMID 41347148, 2025).
lymph node metastases (1 paper, 2022). "CDK7 expression was significantly higher in sqNSCLC with lymph node metastases than in sqNSCLC with N0 stage, indicating a greater aggressiveness." (PMID 36212402, 2022).
malaria (1 paper, 2017). Malaria is a serious and sometimes fatal disease caused by a parasite that commonly infects a certain type of mosquito which feeds on humans. "Consistent with bioinformatic predictions, coimmunoprecipitation of PfCyc1 demonstrated that the PfCyc1/PfMAT1/PfMRK trimeric complex is preserved in malaria parasites, and is similar in constituents to the cyclin H/MAT1/Cdk7 complex." (PMID 28611247, 2017). "Malaria parasites also contain a CDK, PfMRK, that shares the greatest sequence similarity with Cdk7." (PMID 28611247, 2017).
metastatic cancer (1 paper, 2021). A carcinoma which has spread from the original site of growth to another anatomic site. "Altogether, these findings from us and other colleagues suggest that the CDK7/9 inhibitor SNS-032 is a promising therapeutic agent for the treatment of metastatic cancer patients." (PMID 34741018, 2021).
Opportunistic infection (1 paper, 2025). An infection that is caused by a pathogen that would generally not be able to cause an infection in a host with a normal immune system. "SY-1365 also potently kills tumor cell lines, particularly of leukemic origin, and our data now highlight the dual potential of CDK7 inhibitors as chemotherapeutic agents and antifungals, particularly in blood cancer patients at risk of opportunistic infections, including with Cn." (PMID 41171060, 2025).
ovarian endometrioid carcinoma (1 paper, 2025). "These analyses revealed several novel rearrangements that were predicted to result in in-frame protein fusions in ovarian endometrioid carcinomas, including ATAD1–PTEN, the neurofibromin genes NF1 and NF2, as well as cyclin-dependent and polo-like kinase (PLK) genes CDK7 and PLK5." (PMID 40981433, 2025).
peripheral T-cell lymphoma (1 paper, 2020). "However, one study did report a reduction of CDK7 after THZ1 treatment in one type of peripheral T-cell lymphoma but not in another cell type." (PMID 32143485, 2020).
prostate tumor (1 paper, 2014). "Surprisingly, gene expression of CDK7 negatively correlated to CDK2, SKP2, and CCNA2 in both GSE6919 and Singh prostate tumor datasets." (PMID 25271736, 2014).
retinoblastoma (1 paper, 2025). A malignant tumor that originates in the nuclear layer of the retina. "MYCN-overexpressing retinoblastoma cells (MYCNO/E-cells) demonstrated remarkable sensitivity to MYC-targeting therapies, particularly transcriptional inhibitors such as THZ1 (a selective CDK7 inhibitor) and Flavopiridol (a broader-spectrum CDK inhibitor)." (PMID 40943594, 2025).
squamous cell carcinoma (1 paper, 2022). A carcinoma arising from squamous epithelial cells. "Since no studies concerning protein expression of CDK7 in sqNSCLC are published so far, literature regarding CDK7 expression on squamous cell carcinomas (SCC) of other sites is discussed." (PMID 36212402, 2022). "In this study, we aimed to investigate the protein expression of CDK7 in a large cohort of NSCLC incorporating adenocarcinomas (adNSCLC) and squamous cell carcinomas (sqNSCLC) and to correlate its expression with clinicopathological data." (PMID 36212402, 2022).
xeroderma pigmentosum (1 paper, 2018). Xeroderma pigmentosum (XP) is a rare genodermatosis characterized by extreme sensitivity to ultraviolet (UV)-induced changes in the skin and eyes, and multiple skin cancers. "The authors also found reduced trans-activator function of PPARγ in their xeroderma pigmentosum system, and suggested a model where S112ph by CDK7 activates PPARγ function, in opposition to the repressive S112ph mediated by MAPK signaling." (PMID 29895749, 2018).
cancer (180 papers, 2013 to 2026). A tumor composed of atypical neoplastic, often pleomorphic cells that invade other tissues. "CDK7 inhibition has been demonstrated to decrease the development of cancer cells and cause cell cycle arrest during the G2/M phase of the cell cycle." (PMID 40361480, 2025). "Despite being an important modulator of cell proliferation, CDK7 overexpression has been closely linked to various types of cancers." (PMID 40361480, 2025). "In particular, CDK7 is a key regulator of transcription and cell-cycle control, and its deregulation in cancer has been linked to a worse prognosis." (PMID 37519889, 2023). "Inhibition of the dual function cell cycle and transcription kinase CDK7 is known to affect the viability of cancer cells, but the mechanisms underlying cell line-specific growth control remain poorly understood." (PMID 35054996, 2022). "The importance of CDK7 for proliferation of cancer cells is intimately linked to activation of CDKs (CAK function), which is setting the pace in cell cycle progression, as well as to an essential role during pausing and early elongation of RNA polymerase II." (PMID 35054996, 2022). "Overexpression of CDK7 has been associated with a number of cancers and correlated to poor prognosis." (PMID 36279270, 2022). "It is important to note that our analyses of NEAT1_2 splicing and read-through upon CDK7 inhibition were performed in cancer cell lines, which are particularly susceptible to CDK7 inhibition." (PMID 36279270, 2022). "Cyclin-dependent kinase 7 (CDK7) is a kinase involved in transcription, overexpressed in a broad spectrum of cancer types and found to be associated with an unfavourable prognosis." (PMID 36212402, 2022). "CDK7 has been reported to be a potential therapeutic target in transcription-dependent cancers and is associated with a poor prognosis." (PMID 36076237, 2022). "Most importantly, we found that combining THZ1 with Torin1 or serum deprivation had a trend of further reducing CDK7/13 and Ser2P/5P/7P levels and caused the death of much larger number of cultured cancer cells compared to THZ1 alone." (PMID 32143485, 2020). "We have previously observed that the mechanisms of the anticancer activity of CDK7 inhibitors were associated with cell cycle arrest and the apoptosis of various cancer cells." (PMID 33287368, 2020). "Numerous studies have shown that SE-associated genes are preferentially downregulated in cancer cells treated with CDK7 inhibitors." (PMID 32385714, 2020). "Although the mechanisms of anticancer effects via CDK7 inhibition have been associated with cell cycle arrest and apoptosis in various cancers, until recently, biomarkers for determining the sensitivity of cells to CDK7 inhibitors have been unclear." (PMID 33287368, 2020). "It has also been reported that CDK7 is associated with super-enhancers, which play important roles in cancer cell death." (PMID 31399555, 2019). "Cell cycle regulatory protein, CDK7, is linked with DNA repair mechanism which can contribute to cancer risk." (PMID 23561625, 2013). "CDK7 is over-expressed in several cancers and its expression is associated with poor prognosis." (PMID 37488191, 2023). "And 23 of the 25 functional genes were significantly up-regulated in COAD, such as CDK1, CDK2, CDK4, CDK6, and CDK7, which can cause uncontrolled proliferation and may serve as promising targets in cancer therapy." (PMID 32680494, 2020). "Furthermore, CDK7 levels are elevated in a number of cancer types and are associated with clinical outcomes, suggestive of greater dependence on CDK7 activity, compared with normal tissues." (PMID 32385714, 2020).